CXCR5 (C-X-C motif chemokine receptor 5)
Diseases named in the same sentence as CXCR5 in open-access papers (continued):
Sharing a sentence is not in itself a finding about the gene and the disease.
infection (166 papers, 2010 to 2026). The state of being infected such as from the introduction of a foreign agent such as serum, vaccine, antigenic substance or organism. "We found that antigen experience (CD45RA negativity) influenced susceptibility to infection, while CXCR5 expression, used here as a proxy for localization within the lymphoid explants, as well as CD150 expression, did not." (PMID 39253971, 2024). "Of note, the preservation of PD1+CXCR5+CD4+ T cells early during infection has been linked with antibody responses evolving towards broad neutralization." (PMID 35410989, 2022). "However, prior infection is associated with a greater frequency of these cells, a significant reduction in expression of the germinal center chemokine receptor CXCR5, and increased class switching." (PMID 37573434, 2023). "In vitro, GC Tfh cells are more susceptible to infection with HIV‐1 than non‐GC Tfh cells or CXCR5− extrafollicular CD4+ T cells, and in vivo they have been shown to constitute the major CD4 T‐cell compartment for virus replication in both HIV‐1 172, 173 and SIV174, 175 infections." (PMID 28133804, 2017). "Interestingly, both CXCL-13 and CXCR5−/− mice are equally susceptible to infection with either Mtb H37Rv or Mtb HN878 described here, implicating IL-17-independent pathways in CXCL-13 induction during Mtb H37Rv infection." (PMID 24831696, 2014). "In addition, we evaluated whether any of the CAR/CXCR5+ cells were also vRNA+, given that the CD4+ CAR/CXCR5 are presumably susceptible to infection by SIV." (PMID 35130312, 2022). "By contrast, very few (3–6%) of the cDC1 and DN cells expressed the CXCR5 reporter either before or after infection and the numbers of CXCR5 expressing DN and cDC1 cells was very low." (PMID 41012147, 2025). "At 7 and 60+ days post infection, Tfh (CXCR5+ Ly6CLO) and Th1 (CXCR5- Ly6CHI) cells were sorted to isolate genomic DNA for whole genome DNA methylation analysis." (PMID 39677644, 2025). "Particularly high frequencies of TFH cells identified by the expression of the chemokine receptor CXCR5 together with the inhibitory signaling molecule PD-1 were detectable in CLN at day 6 post-infection." (PMID 40092986, 2025). "Runx1 overexpressing SMARTA cells (OE) produced fewer Tcf1+ CXCR5+ and Bcl6+ Tfh cells by percent at 3.5 days post infection." (PMID 39677644, 2025). "As CAR/CXCR5 T cells were unable to suppress HIV during active infection, we wanted to confirm that HIV-infected hDRAGA mice were capable of being virally suppressed." (PMID 40803333, 2025). "In our previous study, we demonstrated that CXCR5 signaling is important in accumulation of lung ILC3s following infection for optimal early Mtb control." (PMID 38407132, 2024). "Heterologous infection or immunization priming also induced an increase of secondary effector CXCR5– Th1 cells that expressed both TBET and IFNγ, which were maintained at a higher magnitude even at later timepoints." (PMID 39283916, 2024). "In the animal model, during infection with Influenza A virus CXCR5+CD8+ T cells arise, actively influencing humoral immunity by shaping antibody responses even in non-follicular microenvironments." (PMID 39845978, 2024). "TRBV6-5 and BCL11B are primarily implicated in the immune response post-infection; PTGDS, EGR3, and CXCR5 modulate the host’s inflammatory response." (PMID 39591343, 2024). "CXCR5, which directs cells to germinal centres in the lymph nodes, increased at 2–5 days and 6–9 days post-infection in S-specific ASC, while showing the opposite trend in RBD-specific B cells." (PMID 38006037, 2023). "Further analysis of CD44+CD4+ T cells in WT animals revealed FoxP3 expression was preferentially enhanced among CXCR5+ populations vs CXCR5- populations (15.40% ±1.93% vs 3.6 ±1.22) at two- and four-weeks post infection." (PMID 37721965, 2023).
infection (continued). "In S-specific cmemSW, the CXCR5+ subset significantly decreased during infection, likely due to either the positioning of the CXCR5+ cells in the lymph nodes and/or generalised activation." (PMID 38006037, 2023). "PR8-OVA infection induced a robust population of donor PD-1+CXCR5+CD4+ T cells in the spleen as well, although the overall OT-II cell response was stronger in the draining medLN than in the spleen." (PMID 37330549, 2023). "It is noteworthy that CXCR5+ cells continued to progressively increase in the lymph nodes draining the infection site as the infection time progressed." (PMID 37691941, 2023). "WT mice also display increased FoxP3+ cell frequencies amongst CXCR5+CD44+CD4+ T cell populations one week post infection compared to μMT animals, suggesting B cells promote TReg development amongst CXCR5+CD44+CD4+ T cells during Brucella infection." (PMID 37721965, 2023). "Collectively, these observations suggest that lymph nodes are the primary location of CXCR5+ cells throughout the course of the infection, whereas CXCR5+TIM-3+ and TIM-3+ cells migrate to peripheral tissue during the chronic phase." (PMID 37691941, 2023). "In summary, these data demonstrate three major populations of Tex cells during experimental infection with L. mexicana, including the previously defined CXCR5+ and TIM-3+ subsets, and also one distinct subset characterized by CXCR5 and TIM-3 co-expression." (PMID 37691941, 2023). "In our previous study, we identified a unique subset of exhausted CD8+ T cells expressing the chemokine receptor CXCR5 during chronic LCMV-cl13 infection." (PMID 36452930, 2022). "CXCL13 and its receptor CXCR5 (which was downregulated in the probiotic group) also play important roles in infection, inflammation, and the immune response." (PMID 33668643, 2021). "Four well-described SNPs that have previously been associated with the outcomes of a CT infection are: TLR2 +2477 G > A (rs5743708), NOD1 + 32656 T −> GG (rs6958571), CXCR5 + 10950 T > C (rs3922), and IL10 − 1082 A > G (rs1800896)." (PMID 33430411, 2021). "Latent and productively infected tonsillar CD4+ T cells displayed similar activation profiles as measured by expression of CD69, CD25, and HLADR, however latent cells showed higher CXCR5 expression 3 days post-infection." (PMID 34531866, 2021). "CXCR3+ TH1-like TFH cells, along with populations of CXCR5+CCR6+ unswitched classical and activated MBCs, were found among the most significant populations associated with increased risk of infection." (PMID 34128836, 2021). "The percentage of CD4+GATA3+IL-4+ Th2 cells and CD4+CXCR5+ Tfh cells, and IL-4 production in the 8-week-old mice significantly increased on day 5 and day 10 after P. yoelii 17XNL infection." (PMID 33430765, 2021). "The frequency of CXCR5+ PD1+ Tfh cells among the CD19−CD4+ CD44+ cells was also significantly reduced in lymph nodes of Tslpr-/- mice on day 10 post-infection compared with WT mice." (PMID 34659250, 2021). "During infections of humans or mice with M. tuberculosis, ILCs are decreased in peripheral blood and migrate to the site of infection in which recruitment is regulated through the CXCL13/CXCR5 axis." (PMID 34671359, 2021). "Using the same experimental strategy, analysis of x31-specific IgG2c in the serum on day 8 post-infection revealed that CXCR5 expression in transferred OT-I cells was required for optimal induction of x31-specific IgG2c." (PMID 34326833, 2021). "The chemokine CXCL13 and its receptor, CXCR5, play a central role in driving humoral immunity during infection and vaccine responses." (PMID 34746181, 2021). "Sorting and transferring PD-1lo/hi subsets into infection-matched hosts based upon CXCR5 positivity validated that PD-1loTim-3−CXCR5+CD8+ Tex marked a self-renewing population that gave rise to PD-1hiTim-3+CXCR5−CD8+ Tex." (PMID 34354714, 2021). "The role of these cells in infection has been shown to be more efficient than their CXCR5– counterpart for viral load control." (PMID 34283810, 2021).
infection (continued). "We also detected a progressive reduction in the expression of LTα, CXCL13 and its receptor, CXCR5, along the course of infection." (PMID 34804009, 2021). "IFNAR1 blockade increases the proportion of TCF1+ CXCR5+ Tim-3− CD8+ T cells during LCMV Cl 13 infection." (PMID 34696381, 2021). "On NK cells, as shown here, PD-1 was often expressed on the same cell subset of CXCR5 + NK cells before infection but mostly on distinct NK cell subsets after SIV infection." (PMID 33013901, 2020). "Hale and colleagues found that, although less prominent during the primary infection, CXCR5+Ly6Cint cells expanded more extensively than CXCR5+Ly6C– cells following transfer and re-challenge with LMCV." (PMID 32983171, 2020). "In SIVmac infection, the frequencies of CXCR5 + NK cells in the gut decreased as compared with those before infection." (PMID 33013901, 2020). "CXCR5intPD-1int TFH cells were the primary source of IL-21 expression early during the course of infection, whereas TFH cells with high expression of CXCR5 and PD-1 (CXCR5highPD-1high) also expressed IL-21 during the resolution phase of the infection." (PMID 31867283, 2019). "Knockdown of STAT1 in mouse T cells results in defective generation of early CXCR5+Bcl6+ TFH cells 2 days after infection." (PMID 30405612, 2018). "We observed a progressive expansion of Fas+GL7+ germinal center cells and CXCR5+PD-1+ TfH cells during the course of infection in wild-type animals compared with uninfected ones." (PMID 29249358, 2018). "Both Cd2ap−/− and control LCMV-specific CD4 T cells differentiated into Ly6C+ TH1 effector cells or TFH cells as defined by CXCR5 and PD-1 expression on day 8 after infection." (PMID 29734372, 2018). "Deleting p19Arf alone did not exhibit detectably impact on TFH cells elicited by the LCMV-Arm infection, and ablating p19Arf in Ezh2–/– cells rectified the frequency of CXCR5+SLAMlo TFH cells and partially restored TFH cell numbers on 4 dpi." (PMID 30575739, 2018). "In contrast, CAR-transduced and CAR/CXCR5-transduced effectors suppressed infection by both strains with equivalent high potency over the 12-day infection, at E:T ratios of 1:1 or 0.2:1." (PMID 29616024, 2018). "Strikingly, DENV-infection of DCs induced a robust CXCR5+PD-1+ subset of differentiated TH cells, which expressed high levels of TFH-specific transcription factor Bcl-6." (PMID 29186193, 2017). "We observed a major expansion of CXCR5+ PD-1+ Tfh cells on day 10 post-infection, relative to uninfected mice." (PMID 28575114, 2017). "Meanwhile, the proportion of CXCR5+ CD4+ Tfh cells in splenic CD4+ T cells kept increasing rapidly from week 0 through week 7 after infection and decreased at 9 weeks post-infection, but continues to increase at 12 weeks post-infection." (PMID 29192177, 2017). "Blocking DENV RNA replication and infection of DCs with DENV RNA replication inhibitor SDM25N abolished the formation of IL-21-secreting CXCR5+PD-1+Bcl-6+ TFH cells." (PMID 29186193, 2017). "Specifically, development of neutralization breadth was associated with increased frequencies of PD-1+CD4+ T cells in early infection, and with higher frequencies of class-switched antibodies in co-cultures of CXCR5+CD4+ T and B cells." (PMID 27938646, 2016). "The fusion constructs demonstrated 5–8-fold improvements in potency compared to GRFT alone in C-C chemokine receptor type 5 (CCR5)-tropic or C-X-C chemokine receptor type 5 (CXCR5)-tropic cell-cell fusion assays and single-round infection assays." (PMID 27783038, 2016). "Multivariate logistic regression showed a correlation of infection with a cluster containing %CD38+ Ki67− of CXCR5− CXCR3− CCR4+ TEM cells as the only positive coefficient with CD38 expression thus determining the significance." (PMID 27064238, 2016). "Consistent with enhanced humoral immunity, we found α-IFNAR treatment resulted in 2 to 3-fold expansions in the frequency and total number of Plasmodium-infection-induced splenic PD-1+CXCR5+Bcl-6+ Tfh cells." (PMID 27732671, 2016).
infection (continued). "Upon investigation of responsive T cells in this infection, we observed a dramatic increase in CXCR5, ICOS, and SLAM." (PMID 26646149, 2015). "In the LNs, early after infection, a significant transient increase of CXCR5+PD-1- is observed in all infected RMs peaking at day 14 (CXCR5+PD-1-, 45.28% ± 5.17%; p = 0.0011) compared to healthy RMs (CXCR5+PD-1-, 29.85% ± 2.26%)." (PMID 26640894, 2015). "After adoptive transfer of OTII cells, host mice were infected with actA-deficient Listeria monocytogenes (ΔActA-Lm) expressing OVA, and the analysis day 4 post infection revealed that virtually all the Foxo1KO OTII cells were CXCR5+." (PMID 25692700, 2015). "TFH cells from old mice did exhibit a small yet statistically significant reduction (11%, P < 0.01) in CXCR5 expression at 6 days post infection." (PMID 26204259, 2015). "Similar to what we found for CXCR5+ T cell responses, percentages of FoxP3+ cells were higher prior to infection, and at day 8 pi in GITRL tg mice compared to their WT counterparts." (PMID 25738498, 2015). "IL-10+ regulatory B (Bregs), CD4+Foxp3+ regulatory T (Tregs), and CD4+CXCR5+Foxp3+ follicular regulatory T (TFR) cells regulate the progression of infection disease." (PMID 25199644, 2014). "Instead it first caused a temporary expansion of CXCR5−IL-4gfp+ Th2 cells and CXCR5+ IL-4gfp+ Tfh cells within the draining LN, followed by the appearance of functionally superior IL-4gfp+ Th2 cells at the infection site 20 days later." (PMID 23516361, 2013). "In contrast, infection with L. sigmodontis significantly increased the percentage of IL-4gfp+CXCR5− Th2 cells expressing PD-1 from d 40 onwards." (PMID 23516361, 2013). "Possessing CXCR5 SNP +10950 (rs3922) with base pair CC, appears to protect against development of tubal pathology following infection." (PMID 23189125, 2012). "We recently reported that C. trachomatis induces expression of CXCL13, the ligand for CXCR5, in human fallopian tube tissue following infection." (PMID 23189125, 2012). "We also examined Cxcr5−/− mice and found that there was a slight delay in resolution of infection and a significant increase in bacterial burden during the infection course compared to WT controls." (PMID 23189125, 2012). "It is possible that frequency and type of infections plus genetic differences in Cxcr5 gene influence iNKT cell activation in humans." (PMID 23189125, 2012). "Mice treated with anti-CXCL13 Ab and Cxcr5−/− mice had increased chronic inflammatory or mononuclear cell scores when harvested 49 days after infection." (PMID 23189125, 2012). "We propose that RSV infection may activate the CXCL13/CXCR5 axis, leading to the recruitment of B cells to the site of infection and exacerbating mucosal damage through an enhanced humoral immune response." (PMID 41360931, 2025). "Similarly, early-activated CD25hi CD4+ T cells (day 3 post-infection), which lack CXCR5 expression, almost exclusively develop into terminal Th1 effector cells, whereas CD25lo cells, which generally express CXCR5, give rise to Tfh and TCM cells." (PMID 40391228, 2025). "While both Tfh (CXCR5+Ly6C-) and Th1 (CXCR5-Ly6C+) cells were readily detectable in the draining lymph nodes following the establishment of memory (day 39 post-infection) after both LCMV infection and GP immunization, some germinal center Tfh (CXCR5+PD-1+) persisted." (PMID 39283916, 2024). "Tissue-resident molecules CXCR5 and CCR6 are expressed on the surface of MAIT cells, and stimulation by E. multilocularis infection causes MAIT cells migrate from the bloods to the site of infection." (PMID 38550591, 2024). "Infection led to robust induction of chemokine and interleukin genes, including Il1b, Il6, Ccl2, Ccl3, Ccl4, Ccl7, Cxcl1, Cxcl2, Cxcl5, Cxcl9, and Cxcl10, and related receptor genes, including Ccr1, Ccr4, Ccr5, Ccr5, Ccr7, Cxcr2, Cxcr5, Il1r2, and Il1rn." (PMID 35487885, 2022).
infection (continued). "Similarly, CXCR5+CCR6+ IgM+ classical and activated MBCs were associated with increased odds of symptomatic infection." (PMID 35475529, 2022). "Interestingly, in this setting, transfer of WT OT-I cells also significantly enhanced IgG2c class switching in the GCB cell compartment on day 6 post-infection, an effect that was also dependent on CXCR5 expression by OT-I cells." (PMID 34326833, 2021). "Critically, infection of mice deficient in CXCR5, the cognate receptor for CXCL13, did not experience increased C. rodentium bacterial burden or pathology." (PMID 30973939, 2019). "Secretion of vIL-8 could allow the recruitment of CXCR5 expressing monocytes and macrophages to the site of infection that could transport the virus to lymphoid organs where B and T cells are infected." (PMID 29326678, 2017). "Our data suggest that CXCR5-expressing conventional DC are required for the efficient delivery of orally acquired prions to FDC in the Peyer's patches of the small intestine in order to achieve host infection." (PMID 28275192, 2017). "However, by day 30 and thereafter, the percentages of both CXCR5+PD-1- and CXCR5+PD-1int subsets declined and reached values lower than those observed before infection, particularly in fast progressors." (PMID 26640894, 2015). "We also observed that some follicle-associated CD4 T cells expressed PD-1 but not CxCR5, particularly by one month after infection in the spleen, and at the chronic phase in lymph nodes." (PMID 24763747, 2014). "However, 12 days post infection, Cd28flox/floxOx40cre/+ mice had reduced numbers of CXCR5+Bcl-6+CD4+ Tfh cells and IFNγ+CD44highCD4+ Th1 cells in the medLN and Th1 cells in the lungs compared to control mice." (PMID 25347065, 2014). "Marked fibrosis was also apparent in all Cxcr5−/− mice following infection." (PMID 23189125, 2012). "This could possibly explain the increased neutrophil and activated cDC numbers seen in the GT of Cxcr5−/− 4 days after infection." (PMID 23189125, 2012). "Furthermore, CXCR5+CD8 T cells appear resistant to immune checkpoint blockade therapy (ICB) induced apoptosis compared to susceptible CXCR5−CD8 T cells and, instead, demonstrate an effector-like phenotype in infection and chronic lymphocytic leukemia." (PMID 36314014, 2022). "No obvious change or reduction in Tfr (CXCR5+PD1+CD4+FOXP3+) cells.Tfr cells may limit the immune effect caused by a persistent antigen or infection." (PMID 36389806, 2022). "We therefore reasoned that if conventional DC were important for the efficient propagation of prions toward FDC in order to establish host infection, this activity would be impeded and disease susceptibility reduced in mice which specifically lacked CXCR5-expressing conventional DC." (PMID 28275192, 2017). "On day 8 post-infection (D8 p.i.) we sort-purified CD45.1+ WT and CD45.2+ Cxcr5−/− migratory CD11c+MHCIIhi DCs isolated from the msLN of the infected mice." (PMID 41012147, 2025). "By 4-weeks post-infection and treatment, PbTII cells and polyclonal CD4+ T cells exhibit GC Tfh (PD1hi CXCR5hi), Tfh/TCM-like (CXCR5+ PD1lo) or Th1-TEM (CXCR5lo CXCR6+) memory phenotypes in the spleen." (PMID 40132035, 2025). "Analysis of transferred cells 5 days after infection demonstrated an increased frequency of pTCM cells expressing CD62L and intermediate for CXCR5 expression amongst transferred Mx1(GFP)+ cells." (PMID 39321257, 2024). "The ligand for CXCR5, namely, CXCL13, is inducible in the murine lung following infection with Mtb (28, –, 30)." (PMID 38407132, 2024). "Further research is required to determine more specific criteria that delineate the TCF1+ progenitor-like CD4+ T-cell subset in our infection model, as other populations of CD4+ T cells express both TCF1 and CXCR5." (PMID 37691941, 2023).